IL10 (interleukin 10)
Diseases named in the same sentence as IL10 in open-access papers (continued):
Sharing a sentence is not in itself a finding about the gene and the disease.
Sepsis (continued). "It has been reported that hMSCs increased CAM mediated by IL-10 and transforming growth factor β (TGFβ) in a hippocampal organotypic culture and sepsis mouse." (PMID 25889720, 2015). "In Gram-negative sepsis IL-6 and TNF-α showed the best AUC values (both 0.93); in Gram-positive sepsis the best AUC was found for IL-6 (0.91); in yeast sepsis IL-6, IL-8, and IL-10 showed the highest AUC values (0.92 for all)." (PMID 26635427, 2015). "In severe sepsis and septic shock, IL-10 and TNF-α have been reported to distinguish between survivors and non-survivors at 28 days." (PMID 26079127, 2015). "On univariate logistic regression analysis, the distribution of genotypes at positions IL-1α (−889 C/T), IL-4 (−1098 T/G), IL-10 (−1082 A/G), allele A of TNF-α (−238) and allele T of IL-10 (−889) were significantly (p < 0.05) predominant in sepsis." (PMID 26561011, 2015). "In rats with hypothermia (32°C) prior to sepsis, the IL-10 levels were significantly increased compared to normothermic rats, altering the cytokines profile, survival, and recruitment of granulocytes suggesting immunosuppression." (PMID 25815330, 2015). "Low doses of CO suppressed inflammatory responses in a murine model of sepsis through inhibition of inflammatory cytokines production as well as increased LPS-induced expression of the anti-inflammatory cytokine IL-10 in various cell types." (PMID 26557739, 2015). "In contrast, TNFα increased while IL-10 and IL-1ß levels were dramatically suppressed by ghrelin showing the beginning of the harmful action of ghrelin treatment in sepsis." (PMID 25844479, 2015). "Haplotype ATA of IL-10 gene in patients with sepsis (16 %) was significantly (p = 0.01) higher in comparison to non-sepsis (1.2 %)." (PMID 26561011, 2015). "Other clinical studies in patients with sepsis found that females had increased levels of IL-10 and lower levels of TNF-α (a pro-inflammatory cytokine) when compared to males, suggesting a more robust IL-10 response in women." (PMID 26462256, 2015). "Theoretically, proinflammatory cytokines (IL-6 and TNF-α) and anti-inflammatory cytokines (IL-4 and IL-10) are increased during sepsis even if IL-4 is often found at low levels probably owing to its short half-life in plasma (5–19 minutes)." (PMID 26635427, 2015). "The distribution of haplotype of the TGF-β, TNF-α, IL-2, IL-4, IL-6 and IL-10 genes were studied in patients with sepsis and non-sepsis." (PMID 26561011, 2015). "In a separate study, circulatory levels of IL-10 paralleled the sepsis score, and its sustained overproduction was deemed a predictor of severity and fatal outcome." (PMID 26322041, 2015). "Four studies reported that balance of inflammatory mediators was closely related to severity and outcome of sepsis, and in these models IL-10 played a critical role to attenuate local and systemic mediators in animals with abdominal sepsis or injury." (PMID 26502877, 2015). "In the acute phase of sepsis, endogenous IL-10 production and exogenous administration can reduce the magnitude of the inflammation." (PMID 25821827, 2015). "It was interesting to notice that IL-10 was higher in patients with severe sepsis, while IL-6 was similar between patients with severe sepsis and simple sepsis." (PMID 24977412, 2014). "The characteristic cytokine markers of sepsis, including IL-1β, IL-6, IL-10 and TNF-α, increased significantly during the experimental timeline." (PMID 24725742, 2014). "This is the potential mechanism for counter regulation of IL-2 versus IL-10 during sepsis or intracranial infection." (PMID 24887408, 2014). "Statistically, compared with those in the control group, the expression levels of TNF-α, IL-10 and NF-κB were significantly higher in the sepsis group (P<0.05)." (PMID 25009602, 2014). "We found significant differences in IL-6 and IL-10 plasma levels between septic patients and healthy individuals (P<0.0001 for both) and between the sepsis and septic shock groups (IL-6:P=0.0036, IL-10:P=0.0096)." (PMID 25476907, 2014).
Sepsis (continued). "The expression levels of TNF-α, IL-10 and NF-κB increased in the sepsis group compared with those in the control group." (PMID 25009602, 2014). "Plasma IL-10 also significantly increased by 8 hours of sepsis from undetectable levels to 5.11 (3.84; 6.82) ng/mL (P <0.001), but had returned to control levels by 24 hours of sepsis." (PMID 25413250, 2014). "In patients with uncomplicated sepsis, the only statistically significant change was a decrease in IL-10 over time (p = 0.016, Skillings-Mack)." (PMID 25343379, 2014). "Along with the cell-free DNA as a biomarker, procalcitonin and interleukin-10 have been investigated as promising biomarkers for patients with bacteraemia or sepsis." (PMID 24520336, 2014). "The relationship between eHSPA12B and prognosis of severe sepsis was analyzed in comparison with IL-6 and IL-10." (PMID 24977412, 2014). "Nor was there supernatant evidence that interphase neutrophils from sepsis patients produced cytokines (IL-2, IL-4, IL-6, IL-10, TNF or IFNγ) when cultured in vitro (unstimulated total cells or enriched CD66b + interphase neutrophils)." (PMID 25084831, 2014). "The area under the curve (AUC) of eHSPA12B in predicting death among patients with severe sepsis was 0.782 (0.654–0.909) in ROC analysis, much higher than that of IL-6 and IL-10." (PMID 24977412, 2014). "In the NaHS groups, the TNF-α and NF-κB levels were significantly reduced whereas the IL-10 level was significantly increased compared with the respective levels in the sepsis group (P<0.05)." (PMID 25009602, 2014). "Németh and colleagues report that bone marrow-derived MSCs reduce mortality and improve organ function in experimental cecal ligation-induced sepsis directly through increasing IL-10 production from LPS-activated macrophages." (PMID 25124290, 2014). "Analysis of cytokine levels by multiplex array showed a rapid, sustained, and significant increase of the putative markers of experimental sepsis, namely IL-1β, IL-6, IL-10, and TNF-α, in FIP mice over a 24-hour period (p < 0.001) versus the sham group." (PMID 24725742, 2014). "Further investigations are required to determine the relationship between cf-DNA, procalcitonin and interleukin-10 as biomarkers for bacteraemia and sepsis patients." (PMID 24520336, 2014). "As an immunomodulator, visfatin induces dose-dependent up-regulation of the pro- and anti-inflammatory cytokines, IL-1β, IL-6, IL-10, and TNF-α in human monocytes: visfatin is associated with sepsis, acute lung disease, atherosclerosis, and cancer." (PMID 24885580, 2014). "Similar tendencies with regard to kinetics and quantities were observed in analyses of serum MCP-1 and IL-10 levels in the sepsis groups (P <0.01)." (PMID 24962182, 2014). "Two hours after sepsis, CLP had more significant expression of genes associated with IL-10 signaling pathways, whereas CS had greater expression of genes related to CD28, apoptosis, IL-1 and T-cell receptor signaling." (PMID 24788351, 2014). "But in the Cox regression, IL-10 was excluded while IL-6 was demonstrated to be correlated to the prognosis of patients with severe sepsis." (PMID 24977412, 2014). "Compared with the control group, the inflammatory cytokine levels of IL-2, IL-6 and IL-10 in patients with sepsis or intracranial infection were significantly elevated (both P<0.05)." (PMID 24887408, 2014). "IL-10 can limit tissue damage by dampening the exaggerated production of pro-inflammatory cytokines observed during sepsis and induce tissue healing." (PMID 24454904, 2014). "Whereas elevation of IL-10 is notable in the profile of cytokine and chemokine responses in human sepsis studies, other critical proinflammatory mediators are consistently suppressed by NTM, and NTM treatment is highly protective against lethal shock." (PMID 25329889, 2014).
Sepsis (continued). "Currently the mechanism by which atenolol increased IL-10 in ovine sepsis is unclear since in isolated macrophages β-agonists stimulate IL-10 release, suggesting that in the whole animal other mechanisms override this effect." (PMID 25413250, 2014). "As analyzed above, CRP and the three cytokines IL-2, IL-6 and IL-10 were differentially related to sepsis and intracranial infection." (PMID 24887408, 2014). "At the time of first sample collection in the ED, gene expression of Interleukin (IL)-10 and Neutrophil Gelatinase Associated Lipocalin (NGAL) were significantly higher in severe sepsis than uncomplicated sepsis." (PMID 25343379, 2014). "Serum concentrations of Resistin, NGAL, IL-6 and IL-10 were higher in all sepsis cases compared to healthy controls (p≤0.003 for all comparisons, Mann Whitney)." (PMID 25343379, 2014). "Secretion levels of the spleen pro-inflammatory cytokines IL-1, IL-6, and TNF-α tallied significantly lower in comparison to the sepsis group, whereas secretion levels of IL-10 anti-inflammatory cytokine increased." (PMID 25153878, 2014). "Although the levels of TNF-α and IL-10 declined towards normal from 8 to 24 hours of sepsis, the increase in IL-6 was maintained throughout the septic period indicating a maintained hyper-inflammatory phase." (PMID 25413250, 2014). "Levels of IL-10 are related to the severity of surgical trauma and the sepsis state and interfere with morbidity after coronary syndromes and myocarditis." (PMID 24092406, 2014). "In agreement with this, we observed that the severity of tubulointerstitial injury induced by albumin overload in a sepsis animal model is also correlated to the level of IL-10." (PMID 25302946, 2014). "In murine models of graft arterial disease and sepsis, CD80 is associated with proinflammatory cytokine stimulation, while CD86 plays a protective role mediated through IL-4 or IL-10 production." (PMID 24472094, 2014). "High levels of IL-10 have been correlated with poor prognosis of sepsis in adults, shown to be a useful predictor of severity in septic shock and death." (PMID 25614712, 2014). "On the one hand, elevated levels of IL-10 prior to GBS infection result in increased survival by reducing sepsis." (PMID 25309541, 2014). "Effects were related to a blocked nitrate/nitrite level increase whereas IL-6, ICAM-1, and IL-10 were similarly induced in all sepsis groups." (PMID 26266921, 2014). "Although we show a persistence of IL-6 and IL-10 elevations, their role in inflammation should be evaluated within the context of the stage of sepsis." (PMID 25182529, 2014). "The study design of this study is based on our previous report, in which the prognosis of septic rats was followed up for 3 days after CLP, and IL-6 and IL-10 were found to be good predictors of sepsis mortality." (PMID 23762108, 2013). "Upon correction for multiple comparisons IL10 gene expression was greater in patients with severe sepsis." (PMID 23935244, 2013). "Our results indicate that NOD2-mediated signals enhance C5a generation by suppressing CD55 expression on neutrophils through IL-1β-dependent or IL-1β-independent IL-10 production during polymicrobial sepsis." (PMID 23675299, 2013). "Fifth, neutrophil depletion in WT mice reduced the levels of IL-1β, IL-10, and C5a, although these depletion effects were dependent on time points of sepsis." (PMID 23675299, 2013). "Rats in the CLP + BHT-H6 group had significantly higher survival rate (80%) and significantly lower levels of both IL-6 and IL-10 at 12 hrs postoperatively than those in the sepsis-control group." (PMID 23762108, 2013). "Upon SB203580 injection, WT mice exhibited reduced RIP2 expression and phosphorylation, and P38 phosphorylation in total peritoneal cells and serum and peritoneal IL-1β, IL-10, and C5a levels during sepsis, whereas these were unaffected in Nod2−/− mice." (PMID 23675299, 2013).
Sepsis (continued). "When considering scenarios with production of systemic proinflammatory mediators, for example, early after surgery, cardiac arrest, or in sepsis patients, anti-inflammatory mediators—namely IL-10 or IL-1βRa—have been concomitantly found." (PMID 24106709, 2013). "The relative small sample size is a limitation of our study, but the dose-dependent effects of BHT on both the survival rate and circulating IL-6 and IL-10 still provide evidence of BHT as a new treatment option for sepsis." (PMID 23762108, 2013). "Early administration of high-dose BHT (CLP + BHT-H6) significantly reduced elevations of IL-6 and IL-10 as compared with the sepsis-control group at 12 hrs postoperatively (bP < 0.05, IL-6: 868.24 versus 3177.64 pg/mL; IL-10: 85.35 versus 229.45 pg/mL)." (PMID 23762108, 2013). "Since plasma levels of interleukin-6 (IL-6) and interleukin-10 (IL-10) were demonstrated as good parameters to predict the outcome of sepsis in our previous study, survival rate and plasma levels of IL-6 and IL-10 of rats were measured in the present study." (PMID 23762108, 2013). "IL-1β and IL-10 concentrations are significantly higher in patients with septic shock than in those with severe sepsis." (PMID 23675299, 2013). "IL-10 is known to be an important regulator of inflammation in sepsis, and plays an important role in down-regulating the expression of monocyte-derived TNF-α and IL-1." (PMID 24069500, 2013). "In conclusion, NOD2-mediated signals increase C5a levels by suppressing CD55 expression on neutrophils via IL-1β-dependent or IL-1β-independent IL-10 production by neutrophils, thereby aggravating sepsis." (PMID 23675299, 2013). "The IL-6/IL-10 ratio seems to indicate a balance in sepsis between pro- and anti-inflammatory cytokines." (PMID 23374857, 2013). "Anti-PD-L1 antibody administration decreased ALT and AST release in CLP mice, decreased the levels of tumor necrosis factor (TNF)-α, interleukin (IL)-6, and IL-10 mRNA in liver after sepsis challenge." (PMID 24324295, 2013). "Thirty-six hours after sepsis there was a return to baseline of all proinflammatory parameters and an increase of the anti-inflammatory IL-10." (PMID 23935245, 2013). "Recently, both IL-6 and IL-10 elevations were found to be significantly correlated with mortality of sepsis." (PMID 23762108, 2013). "Several studies have reported that IL-10 suppresses immune responses during sepsis by activation-induced apoptosis of T cells, reducing MHC class II expression on APCs, decreasing IFN-γ production, and deactivating monocytes." (PMID 23675299, 2013). "Second, Il-1r−/− mice exhibited lower serum and peritoneal IL-10 and C5a levels during sepsis, although IL-1β levels were similar in Il-1r−/− and WT mice." (PMID 23675299, 2013). "It generally accepted that IL-1β-mediated systemic inflammatory responses and cardiac dysfunction, and IL-10-mediated immune suppression account for the high mortality in sepsis." (PMID 23675299, 2013). "SNPs in the genes for TLR2 (rs3804099), TLR5 (rs5744105), IL-10 (rs1800896), and PLA2G2A (rs1891320) were associated with sepsis." (PMID 24310803, 2013). "APC has been shown to upregulate anti-inflammatory mediators, like IL-10 in blood monocytes in patients with severe sepsis." (PMID 22645700, 2012). "IL-10 was significantly elevated after 12 h of sepsis in the 10% HES200 group compared to 6% HES130, RAc and SHAM." (PMID 22277099, 2012). "This may be a valuable therapeutic strategy because inhalative IL-10 administration may solve the dilemma of the two-edged sword: end organ protection is possible without altering the systemic inflammatory response and the susceptibility to infection and sepsis." (PMID 22046081, 2012). "Still, T cell-induced cytokine profiles were similar when sepsis and control CD1a+ DC were used, with comparable production of IL-10 and IFN-γ." (PMID 23071758, 2012).
Sepsis (continued). "During acute sepsis, the release of pro-inflammatory cytokines, such as IL-1β and IL-6, and the immune modulatory cytokine, IL-10, by innate immune cells such as macrophages, granulocytes and natural killer (NK) cells has been well documented." (PMID 22742734, 2012). "Both IL-6 and IL-10 were significantly higher in patients with sepsis and both decreased markedly from enrollment to the end of the study." (PMID 22742734, 2012). "High plasma IL-10, MIF and IL-6 levels have been associated with severity and a poorer outcome in sepsis and were chosen for the present study." (PMID 22701553, 2012). "In trauma patients, it seemed that there is a relation between the level of IL-10 expression, the development of sepsis and death." (PMID 22431998, 2012). "The up-regulation of TNF-α, IL-1α, IL-1β, CXCL-10, SOCS3, IL-10 at 1 and 2 h in the present study was similar to that observed in blood profiles of sepsis patients at early stages." (PMID 23009705, 2012). "In sepsis, BMSCs were shown to upregulate IL-10 in macrophages via prostaglandin E2-mediated reprogramming." (PMID 23319959, 2012). "In CLP mice, levels of pro-inflammatory factors IL-6 and TNF-alpha were significantly increased, while the anti-inflammatory factor IL-10 was decreased in sepsis in both the plasma and peritoneal cavity 24 h after surgery." (PMID 22590504, 2012). "This phenomenon can be explained by the fact that male rats require more aggressive immunostimulation to produce sufficient anti-inflammatory cytokines, such as IL-10, to reduce their mortality from sepsis." (PMID 22666548, 2012). "A sustained high plasma IL-10 level is the main predictor of severity and poor outcome in patients with severe sepsis." (PMID 21939530, 2011). "At 24 h after induction of sepsis, the IL-10 levels were significantly higher in WT mice than in plg-/- mice, while the levels of IL-10 were similar between the two genotypes in the infection model." (PMID 21931850, 2011). "Serum levels of sCD40L, tumour necrosis factor-alpha and interleukin-10, and plasma levels of tissue factor were measured in 186 patients with severe sepsis at the time of diagnosis." (PMID 21406105, 2011). "More studies are needed to elucidate the relationship of IL-10 response with outcome in patients with severe sepsis." (PMID 21939530, 2011). "For example, in the cecal ligation/perforation (CLP) sepsis model, mice genetically deficient in MCP-1 showed lower IL-10 production in peritoneal macrophages and increased mortality." (PMID 20950459, 2010). "Some authors suggest that although CD4+CD25+ Tregs induced by IL-10 seem to contribute to sepsis-induced suppression of lymphoid dependent immunity, the removal of CD25+ cells does not provide a survival advantage or disadvantage." (PMID 20064232, 2010). "As anti-inflammatory cytokines can also play a role in the response to severe sepsis we next looked at the levels of IL-10, IL-4, IL-11 and IL-5." (PMID 21124895, 2010). "Recent studies have documented elevated levels of IL-1 beta, IL-6, IL-7, IL-8, IL-10, IL-13, and tumour necrosis factor-alpha in septic shock patients than in those with severe sepsis." (PMID 20490277, 2010). "Using the CLP model of sepsis, we found that CB2 receptor activation by endogenously released cannabinoids contributes to mortality, bacterial invasion, IL-10 production, and immune cell death in sepsis." (PMID 19641602, 2009). "IL-10 has been shown to be elevated after trauma and is well correlated with the development of sepsis and outcome in patients with major trauma." (PMID 19939284, 2009). "In fact, it has been shown that IL-1Ra treatment before inoculation enhances mortality in experimental sepsis and IL-10 neutralization has also been shown to enhance survival to sepsis." (PMID 19865485, 2009). "For example, IL-10 knockout mice have an increased extent of inflammation illness and higher mortality rates after experimental sepsis." (PMID 19725984, 2009).